LEP (leptin)
Diseases named in the same sentence as LEP in open-access papers (continued):
Sharing a sentence is not in itself a finding about the gene and the disease.
Obesity (continued). "Dimerized STAT3 acts as a transcription factor and upregulates SOCS3 expression, which can induce hypothalamic leptin resistance linked to obesity." (PMID 33379198, 2020). "The possible mechanism accounting for the protective association between obesity and cognition was explained by the hormone leptin which is mainly secreted by the adipose tissue." (PMID 31986486, 2020). "In cases of leptin deficiency, the PNS-induced modulation of the gut microbiota exerts negative effects on thermogenesis and browning in white adipose tissue (WAT), which indicates that PNS fail to reduce obesity in leptin gene-deficient mice." (PMID 33042284, 2020). "Obesity is associated with higher levels of insulin and leptin, while sensitivity to these hormones is reduced." (PMID 32721994, 2020). "Congenital deficiency of leptin or Lepr owing to loss-of-function mutations in rodents and humans leads to profound metabolic dysfunctions, including hyperphagia, obesity, insulin resistance and infertility." (PMID 32746867, 2020). "We also investigated the relationship between other obesity-associated markers and semen quality parameters, serum reproductive hormones, lipids and leptin." (PMID 32993674, 2020). "Increased amounts of adipose tissue, also associated with obesity, acts as an endocrine organ, releasing hormones such as leptin, and produces increased levels of oestrogen via the conversion of androstenedione." (PMID 32036786, 2020). "Here, we used leptin-deficient (ob/ob) mice as an animal model for over-feeding to evaluate the potential of AC in anti-obesity roles in leptin-deficient (ob/ob) mice." (PMID 32164196, 2020). "On the other hand, recombinant leptin treatment is widely established and approved to treat obesity causes by leptin deficiency." (PMID 33192583, 2020). "At baseline 4% had low-normal levels of leptin in spite of obesity, which suggest relative leptin deficiency as a cause of obesity." (PMID 32934313, 2020). "Then, we tested H.alvei HA4597 in two mouse models of obesity: genetic, leptin-deficient ob/ob mice and nutritional, high-fat diet (HFD)-induced obesity." (PMID 31911661, 2020). "Obesity status and female sex interact with LEP polymorphisms, leading to higher leptin level either in all individuals or in obese women." (PMID 31914480, 2020). "Mice with homozygous mutation in leptin gene (ob/ob) exhibit not only obesity-induced insulin resistance but also hypothermia." (PMID 32698539, 2020). "In this regard, it was previously reported that HFD-induced obesity causes insulin insensitivity and reduced leptin secretion, resulting in decreased appetite in mice." (PMID 33003300, 2020). "In a meta-analysis of breast cancer study, higher leptin levels were associated with obesity and lymph node metastases." (PMID 33050319, 2020). "The involvement of Hmga2 in fat tissue differentiation is also stressed by the observation that Hmga2 deficiency renders the mouse resistant to diet-induced obesity and mitigates the effect of leptin deficiency." (PMID 31963852, 2020). "The p.N103K LEP mutation causes obesity due to biological inactivity, but in the presence of high circulating levels of the mutant leptin hormone." (PMID 31067764, 2019). "The knockdown of LepR specifically in endothelial cells of the BBB was functionally linked to impaired transport of leptin into the CSF and LepR positive brain regions, and aggravated obesity when mice were exposed to high fat diet." (PMID 30283080, 2019). "The association of increased leptin levels in obesity and increased risk of neurodegenerative diseases in obese individuals has been widely discussed." (PMID 31447640, 2019). "Obesity and its associated complications, such as IR, are associated with increased plasma leptin concentrations." (PMID 30862092, 2019).
Obesity (continued). "Some mutations that cause massive obesity are also useful to study the pathophysiological mechanisms of hepatic steatosis, including mice carrying loss of function of the leptin gene (Lepob/ob mice) or the leptin receptor gene (Leprdb/db mice)." (PMID 31756971, 2019). "Postnatal HFD feeding induces obesity and obesity is associated with increased circulating leptin levels." (PMID 31781033, 2019). "The involvement of SCD1 in the regulation of obesity has been demonstrated by the increase of its activity in the adipose tissue of various animal models of obesity, such as leptin-deficient ob/ob mice, which develop an obese phenotype early on in life." (PMID 31554181, 2019). "Obesity, T2DM, and MetS have been found to be associated with deregulated serum leptin levels, while leptin resistance has been recognized as an important factor in obesity." (PMID 31408957, 2019). "Researchers have identified genes of the leptin (LEP)–Melanocortin pathway associated with the monogenic forms of obesity by their effect on food intake and energy homeostasis (Huvenne, Dubern, Clément, & Poitou, 2016)." (PMID 31070016, 2019). "For instance, deletion of leptin-induced vagal activation causes hyperphagia, obesity, diabetes, and infertility." (PMID 30700738, 2019). "Previous studies have shown that as obesity increases, skeletal muscle loss leads to an increase in inflammatory adipocytes, such as leptin, tumor necrosis factor alpha (TNF-α), and interleukin (IL-6), and reduces concentrations of adiponectin or IL-15." (PMID 31269909, 2019). "Traditionally, the two most important adipokines associated with the development of breast cancer related to obesity are leptin, which will be extensively reviewed below, and adiponectin." (PMID 31380268, 2019). "It has been shown that serum leptin levels are increased in obesity, and higher BMI has been found to be associated with PE and, according to the results of our study, also with gestational hypertension." (PMID 31737362, 2019). "While the mechanisms underlying the development of leptin resistance and impact on obesity development are still being elucidated, literature suggests that high leptin levels in obese states are associated with adverse metabolic risk." (PMID 31851703, 2019). "Different pathogenic mutations have been discovered in LEP for its role in obesity like A19G variation in 5‛UTR region and G-2548A in promoter region." (PMID 32042833, 2019). "Body fat loss and increased insulin sensitivity are the most effective and natural methods of reversing obesity-associated inflammation and leptin downregulation, and thus, adiponectin upregulation." (PMID 31121868, 2019). "Using leptin-deficient ob/ob female mice fed a HFD, we investigated the effects of estradiol and obesity (due to leptin deficiency) on body weight, energy intake, and gut microbiota in the present study." (PMID 31882890, 2019). "Accordingly, early postnatal leptin blockage in rats leads to long-term leptin resistance and susceptibility to diet-induced obesity." (PMID 30694175, 2019). "Some practices and therapies as physical exercise and drug treatment can reduce leptin levels in obesity models, and this effect is associated with improvement in leptin signaling." (PMID 31191459, 2019). "It took several years for this to become evident, because the few patients with obesity due to loss-of-function mutations in the leptin gene did indeed have dramatic responses to daily injections of recombinant leptin." (PMID 30357355, 2019). "Studies on the leptin-deficient (ob/ob) mouse model for obesity have shown that, compared to normal wild type mice, ob/ob mice have markedly different gut microbial composition and increased capacity to harvest energy from food." (PMID 33499919, 2019).
Obesity (continued). "Understanding the mechanism of action of celastrol will not only provide insights into the underlying biology of leptin signaling and resistance, but will create new avenues for the development of effective therapies for obesity." (PMID 31488870, 2019). "In the subgroup of subjects with metabolically healthy obesity, a high leptin/adiponectin ratio was significantly associated with an increased risk of arterial hypertension during follow-up compared to metabolically healthy normal-weight children." (PMID 31262082, 2019). "Obesity promotes various pathways of cellular leptin resistance therefore restoring leptin sensitivity causes weight loss by affecting appetite." (PMID 31226166, 2019). "According to a study, the deficiency of leptin synthesis is related to obesity and sterility in ob/ob knock-out mice." (PMID 31287259, 2019). "To follow up on our findings in human obesity, we also examined hepatic expression levels of Mboat7 in obese leptin-deficient mice and high fat diet-fed rats." (PMID 31621579, 2019). "The study aims to determine salivary IL-6 and leptin as obesity associated inflammation markers using a new non-invasive method with clinical applications in case of children diagnosed with overweight and obesity." (PMID 30605486, 2019). "The present study was designed to evaluate possible association among salivary leptin concentrations, obesity, periodontal disease and some bone characteristics." (PMID 30758470, 2019). "Among those variables, multivariate analysis found that leptin, sOBR, and kisspeptin were independently associated with obesity." (PMID 31871451, 2019). "In a study, genetic variations (rs17817449 and rs142085) occurring in the loci of the FTO gene were reported to contribute to the etiology of obesity by increasing the level of plasma leptin and causing the insulin resistance." (PMID 31810473, 2019). "Plasma leptin concentration increases in proportion to the fat mass expansion in obesity which is frequently associated with sympathetic overactivation." (PMID 31682617, 2019). "The results indicate a strong association between maternal serum leptin levels and obesity and between cord blood leptin levels and birth weight." (PMID 31697751, 2019). "The ob/ob mouse is a genetic obesity mouse with a deficiency of the leptin gene that constitutively develops obesity." (PMID 31109074, 2019). "One of the peripheral functions of leptin is a regulatory role in the interplay between energy metabolism and the immune system, in part responsible for the inflammatory state associated to obesity." (PMID 31380268, 2019). "The CXCL12 rs501120 C, FTO rs9939609 A, and LEP rs7799039 A alleles were significantly associated with T2D in the obesity group under a recessive inheritance model." (PMID 30764545, 2019). "This phenomenon has been explained by the fact that BDNF is also regulated by leptin, therefore leptin resistance—as one of the obesity-associated factors—shall be considered in future studies." (PMID 30767081, 2019). "In contrast, obesity is associated with high serum leptin levels (hyperleptinemia) and low serum adiponectin levels (hypoadiponectinemia), and leptin has been generally thought to be a cause of many types of CVD associated with obesity." (PMID 31703113, 2019). "The molecular mechanisms underlying the relationship between obesity and breast carcinogenesis involves estrogens, insulin, leptin, adiponectin, and inflammatory cytokines." (PMID 31380268, 2019). "Here, we described the ability of leptin, the most important adipokine closely related to obesity-associated breast cancer, to influence breast cancer development by modulating exosome biogenesis and release." (PMID 31336913, 2019). "Mutations of the LEP gene have been associated with obesity in different populations; it is a multifactorial disease that constitutes a major public health problem." (PMID 31871931, 2019).
Obesity (continued). "Loss-of-function mutation of leptin in mice causes hyperphagy and obesity (in Ob/Ob mice), as does that of its receptor (in Db/Db mice)." (PMID 31656948, 2019). "Such pronounced and various changes of methylation-associated parameters clearly indicate that the development of obesity is connected with the sophisticated orchestration of biological events associated with leptin regulation." (PMID 31408957, 2019). "An association of leptin with obesity, infertility, and other endocrine functions has been reported." (PMID 32025443, 2019). "Women with high leptin levels, lower circulating levels of adiponectin in serum due to obesity, hyperinsulinaemia, and high leptin/adiponectin ratio have the highest risk of developing endometrial cancer." (PMID 30934676, 2019). "A previous study has demonstrated that WFA improves insulin sensitivity and promotes weight loss by acting as a leptin sensitizer, while the present study investigated further the insulin sensitizing and anti-obesity effects of WFA." (PMID 31226166, 2019). "High levels of leptin resulting from leptin resistance and reduced adiponectin levels have been associated with obesity pathophysiology disorders." (PMID 31489938, 2019). "Leptin is a nutritional cytokine encoded by the obesity gene whose concentration in the tumor microenvironment is closely related to the occurrence and progression of cancer." (PMID 31119158, 2019). "Leptin makes a major contribution to the elevated RSNA in obesity associated hypertension and all three hormones can be elevated." (PMID 30804811, 2019). "Several theories have been postulated to explain these obesity-associated cardiac abnormalities, such as alterations in myocardial substrate utilization, mitochondrial dysfunction, neurohormonal dysfunction, leptin resistance, and impaired insulin signaling." (PMID 31379826, 2019). "In our recent cohort study of children from China with risk for metabolic syndrome (MS), we also found that short sleep duration was associated with both increased obesity risk and leptin concentrations." (PMID 31285522, 2019). "PI3K pathway has been considered an important link between obesity, leptin and increased risk of breast cancer." (PMID 31380268, 2019). "From 1997 until today, 8 mutations were revealed in LEP gene all causing extreme obesity in infants, 7 of which interfered with the expression or secretion of Leptin resulting in low to undetectable serum levels of this protein." (PMID 31871931, 2019). "Obesity is associated with increased leptin levels, which suggests another pathophysiologic mechanism to hypogonadism in adolescents with obesity." (PMID 31052376, 2019). "In summary, our longitudinal study supports the notion that increased sleep time during childhood has advantageous effects on protecting against a genetic predisposition to obesity, with leptin playing a key role in the process." (PMID 31285522, 2019). "In Mexican women, G carriers had higher leptin levels in serum, while A carriers showed lower risk of obesity, suggesting that the A allele is an obesity protective factor in Hispanic populations." (PMID 30764545, 2019). "They reported that genetic variations in the loci of the FTO gene (rs9939609, rs17817449, and rs142085) contribute to the aetiology of obesity by affecting the level of plasma leptin and causing insulin resistance." (PMID 31810473, 2019). "The deregulated production of leptin is associated with disorders of carbohydrate metabolism with the resulting accumulation of adipose tissue and overweight or obesity." (PMID 31697751, 2019). "Our observations indicate that their severe obesity is due to a congenital deficiency in the production of leptin." (PMID 31067764, 2019). "This review aims to examine literature concerning leptin and immunological status in obese dogs, in particular for the aspects related to obesity-associated diseases." (PMID 31091785, 2019).
Obesity (continued). "Obesity is a major risk factor for asthma, and elevated leptin, an adipokine mainly produced by adipocytes, correlates with allergic asthma." (PMID 30978945, 2019). "Pro-inflammatory adipokines—for example, leptin—have been implicated in the development of both obesity-related type 2 DM and CVD." (PMID 31877943, 2019). "Although several low-frequency mutations associated with very low leptin levels, and extreme obesity phenotypes have been identified, the effect of common polymorphisms on circulating leptin levels and obesity phenotypes is less clear and inconsistent." (PMID 31766143, 2019). "Accordingly, several researchers investigated leptin as a candidate prognostic biomarker for obesity risk in later life." (PMID 31817641, 2019). "Obesity and diabetes were associated with increased leptin and decreased adiponectin plasma levels, higher protein expression of leptin and IL-6 in SAT, and higher visfatin protein expression in EAT." (PMID 31533725, 2019). "Mouse models that feature obesity, hyperglycemia, hyperinsulinemia, particularly db/db (leptin-deficient) mice, and Zucker fa/fa (loss-of-function leptin receptor) rats resemble type 2 diabetic conditions in humans." (PMID 31718027, 2019). "Monogenic or oligogenic non-syndromic forms of obesity have been described in patients with homozygous or heterozygous compound loss-of-function mutations in genes that are part of the leptin melanocortin pathway: LEP, LEPR, POMC, PCSK1 and MC4R13." (PMID 31341224, 2019). "Overexpression of leptin and phosphorylated ObR is implicated in gastric cancer in humans and in murine model, and diet-induced obesity causes precancerous lesions in the stomach in mice." (PMID 31141984, 2019). "Other miRNAs are likely to be regulated by the same cascade downstream of both insulin and leptin, contributing to the correlation between obesity/IR and cancer risk." (PMID 31207998, 2019). "Elucidation of the molecular mechanisms underlying leptin resistance is of vital importance for the application of leptin as an effective treatment for obesity." (PMID 31717265, 2019). "They found that this locus is a good marker for association studies of LEP with metabolic diseases such as obesity and type 2 diabetes." (PMID 32042833, 2019). "The adipokine leptin has even been proposed as a possible causative link between obesity and osteoarthritis, being associated with structural knee joint abnormalities, pain pathways, and an increased prevalence of back pain in women." (PMID 31277706, 2019). "The Let-7 family has been shown to act as a pro-adipogenic factor targeting high-mobility group AT-Hook 2 (HMGA2) protein, which reduces fat mass in obese leptin-deficient mice suggesting, once again, a role for leptin and obesity in CRC." (PMID 31207998, 2019). "Obesity is associated to a low-grade inflammation that alters the expression of adiponectin, leptin, IL-6, Monocyte Chemotactic Protein 1 (MCP1), TRAIL, LIGHT/TNFSF14, OPG, and TNFα." (PMID 31130918, 2019). "Actually, augmented circulating levels of leptin in obesity caused hypothalamic leptin resistance, reducing the anorexigenic and energy expenditure signals and aggravating obesity." (PMID 31191220, 2019). "It has been proven that leptin can be associated with the complications resulting from obesity, such as hypertension and cardiovascular diseases." (PMID 31252598, 2019). "The development of leptin resistance in obesity is also associated with an increase in endoplasmic reticulum (ER) stress in animal models." (PMID 31717265, 2019). "In other studies the cells were stimulated also for a short period and/or with high concentrations of leptin, above the physiological or obesity-associated levels." (PMID 31920961, 2019). "The association of SRH with leptin was relatively strong among males (n = 1763), or people with obesity (n = 2298) or high alcohol consumption (n = 158) or elevated systolic blood pressure (n = 2441)." (PMID 31832026, 2019).